IRF8 (interferon regulatory factor 8)
Diseases named in the same sentence as IRF8 in open-access papers (continued):
Sharing a sentence is not in itself a finding about the gene and the disease.
Splenomegaly (4 papers, 2012 to 2021). Abnormal increased size of the spleen. "Although the absolute numbers of LKs and LT‐HSCs were increased due to splenomegaly, the sum of HSCs in bone marrow and spleen was still significantly reduced in Irf8−/− mice." (PMID 34365741, 2021). "Moreover, even at advanced age and regardless of whether they had been infected, IRF8-deficient mice showed no signs of disease, including splenomegaly and autoantibodies to erythrocytes or chromatin." (PMID 30199535, 2018). "Notably, despite a slight increase of peripheral white blood cell counts and splenomegaly in the recipient mice transplanted with Irf8−/− HSCs, they did not exhibit any clear myeloid bias, which was consistent with previous research." (PMID 34365741, 2021). "In addition, the body weights of the Irf8fl/fl;Lyz2cre/+ mice during development were not different as compared to the control mice, while splenomegaly was observed in the Irf8−/− but not the Irf8fl/fl;Lyz2cre/+ mice (data not shown)." (PMID 27502007, 2017).
systemic sclerosis (4 papers, 2015 to 2024). A chronic disorder, possibly autoimmune, marked by excessive production of collagen which results in hardening and thickening of body tissues. "IRF8 is also a significant locus in European GWAS for systemic sclerosis, but rs10917688 only shows an association in the presence of the risk allele of IRF8 in the Japanese population." (PMID 38296975, 2024). "Prioritizing the top 5% of SNPs of IRF8 binding sites in B cells improves the fitting of the polygenic risk scores, underscoring the roles of B cells and IRF8 in the development of systemic sclerosis." (PMID 38296975, 2024). "We have highlighted one such example at the IRF8 GWAS locus for systemic sclerosis, but a more systematic examination of the data motivated by interests in particular diseases and/or traits is needed." (PMID 26474488, 2015).
acute lymphoblastic leukemia (3 papers, 2018 to 2023). Leukemia with an acute onset, characterized by the presence of lymphoblasts in the bone marrow and the peripheral blood. "Suppressed interferon regulatory factor 8 (IRF8) contributes to cell proliferation and leukemogenesis of T‐cell acute lymphoblastic leukemia (T‐ALL) via transcriptional regulation of PIK3R5 and activation of phosphatidylinositol 3‐kinase (PI3K)/AKT pathway." (PMID 36478193, 2023). "Analysis of IRF8 expression in GSE13425 showed that IRF8 expression levels were markedly lower in T‐ALL than in B‐cell acute lymphoblastic leukemia (B‐ALL) with cytogenetic subtypes such as TEL‐AML1, hyperdiploid, and BCR‐ABL." (PMID 36478193, 2023). "IRF8 has been implicated in diffuse large B cell lymphoma (DLBCL) and pre-B cell acute lymphoblastic leukemia (Pre-B ALL)." (PMID 36078039, 2022).
autoimmune uveitis (3 papers, 2016 to 2017). An autoimmune form of uveitis (disease). "The data are also in agreement with previous studies showing the important role of IRF8 in the control of ocular inflammation in mice with experimental autoimmune uveitis (EAU)." (PMID 28881647, 2017). "VKH disease was chosen as an autoimmune uveitis entity, whereby we focused on DNA methylation as a possible mechanism controlling the function of IRF8." (PMID 28432342, 2017). "Our findings support earlier observations showing the important role of IRF8 in the control of experimental autoimmune uveitis (EAU) mice model." (PMID 28432342, 2017). "Studies in the experimental autoimmune uveitis model in mice showed that intraocular inflammation is exacerbated in mice with a targeted IRF8 deletion in their T cells whereby disease enhancement correlated with Th17 cell expansion and a decrease in T regulatory cells." (PMID 28432342, 2017).
bladder cancer (3 papers, 2011 to 2025). "In this study, we initially utilized the TCGA bladder cancer cohort to investigate potential DNA methylation markers associated with BCa in the ZNF671, OTX1, and IRF8 genes." (PMID 38472940, 2024). "Biomarkers with high sensitivity and specificity in multiple panels include RUNX3, SOX1, IRF8, and DAPK; these were used specifically for diagnosis of bladder cancer." (PMID 40141826, 2025).
Burkitt lymphoma (3 papers, 2013 to 2024). A rare form of malignant mature B-cell non-Hodgkin lymphoma. "Here we first utilized an Akata (EBV+) cell line, a Burkitt’s lymphoma cell line of type I latency, as a model system to investigate the role of IRF8 in the EBV lytic cycle." (PMID 29357389, 2018).
cerebral malaria (3 papers, 2013 to 2022). A sequestration of Plasmodium falciparum in the brain, which can cause coma and/or seizures. "Evidence from a genome-wide association study (GWAS) in humans has shown an association of IRF8 variants to chronic inflammatory conditions, such as multiple sclerosis, cerebral malaria, and peripheral nerve injury." (PMID 34379515, 2021). "Simultaneously, deficiency of IRF8 in mice conferred them resistance to peripheral nerve injury and experimental cerebral malaria." (PMID 34379515, 2021). "We have used an experimental model of murine cerebral malaria (ECM) induced by infection with Plasmodium berghei ANKA (PbA) to investigate the role of Irf8 in pathological inflammation." (PMID 23853600, 2013). "To assess the contribution of Irf8 to pathological inflammation, we infected BXH2 mice with PbA parasites, the murine agent of experimental cerebral malaria (ECM)." (PMID 23853600, 2013).
experimental autoimmune encephalomyelitis (3 papers, 2019 to 2022). An autoimmune demyelinating disease of the central nervous system that is produced experimentally in animals by the injection of homogenized brain or spinal cord in Freund's adjuvant. "For instance, IRF8 is up-regulated and contributes to the disease progression in the mouse model of experimental autoimmune encephalomyelitis." (PMID 30484118, 2019). "Reportedly, interferon regulatory factor-8 (IRF-8), as a transcriptional factor, can promote IL-12, IL-23, CCL6 and CCL9 expression and induce inflammatory diseases such as experimental autoimmune encephalomyelitis (EAE) 16-18." (PMID 35637950, 2022).
gastric cancer (3 papers, 2022 to 2025). A primary or metastatic malignant neoplasm involving the stomach. "Soon after, it was discovered that a low expression of IRF8 in gastric cancer patient PBMCs correlated with enhanced disease progression." (PMID 35757757, 2022). "Taken together, these observations indicate that advancing gastric cancer microenvironments reduce IRF8 expression in CTLs and suppress antitumor immunity by promoting exhaustion." (PMID 35757757, 2022). "IRF8 directly participates in the acquisition of M1 macrophage functions, and was recently used to characterize M1 TAMs in gastric cancer." (PMID 36230752, 2022).
glioblastoma (3 papers, 2021 to 2025). The most malignant astrocytic tumor (WHO grade IV). "Silencing IRF8 in glioblastoma stem cells reduces CCL2 expression, significantly weakening the immune evasion capability of CSCs and directly confirming the pro-oncogenic role of IRF8 in these cells." (PMID 41368628, 2025). "These conflicting observations have prompted investigations into the dual roles of IRF8 in glioblastoma multiforme, underscoring the urgent need to clarify its function in both CSCs and differentiated tumors." (PMID 41368628, 2025). "Reduced methylation of the interferon regulatory factor 8 (Irf8) promoter results in increased Irf8 expression in aggressive forms of glioblastoma multiforme (GBM)." (PMID 40564171, 2025). "In glioblastoma, glioblastoma stem cells activate the expression of IRF8 via epigenetic immune editing in response to immune attacks from the host." (PMID 41368628, 2025). "Moreover, studies by Lee, Ramaswamy, and Bredel all found that IRF8 and IRF9 levels were significantly increased in glioblastoma or anaplastic oligoastrocytoma." (PMID 33902005, 2021).
HIV-1 infection (3 papers, 2009 to 2024). The type species of lentivirus and the etiologic agent of acquired immunodeficiency syndrome (AIDS). "Type I IFN signaling, in turn, is associated with the recruitment of IRF8 to the ISRE located in the GLS and a shift to low-level or latent HIV-1 infection." (PMID 33472928, 2021). "In addition, IRF-8 gene expression was not induced by HIV-1 infection but was expressed at a higher amount." (PMID 19404407, 2009).
Hyperglycemia (3 papers, 2022 to 2024). An increased concentration of glucose in the blood. "IRF8 is an important regulatory gene for the development of dendritic cells, which play a crucial role in the regulation of insulin secretion and hyperglycemia." (PMID 37113991, 2023). "Irf8-/- mice did not develop metabolic syndrome and we did not observe any deficiency in enteroid formation, most likely because the defects in enteroid formations in Batf3-/- mice are driven by metabolic changes including hyperglycemia." (PMID 35812447, 2022).
liver fibrosis (3 papers, 2022 to 2023). "IRF8, NR4A2, IKZF3, and REL may be involved in the transcriptional regulation of NK cells in liver fibrosis." (PMID 35903097, 2022).
pancreatic cancer (3 papers, 2018 to 2022). "We also found IRF8 expression was decreased in the blood pre-DCs of pancreatic cancer patients and the extent of IRF8 downregulation correlated with blood pre-DC numbers." (PMID 29593283, 2018). "Extending upon this finding, we found reduced IRF8 expression in circulating pre-DCs also correlates with reduced overall and recurrence-free survival in pancreatic cancer patients." (PMID 29593283, 2018).
parasite infection (3 papers, 2020 to 2024). "Previously, we demonstrated that host resistance is mediated by T-bet–dependent ILC-derived IFN-γ by maintaining IRF8+ conventional type 1 dendritic cells during parasitic infection." (PMID 38687282, 2024). "IRFs have been shown to play several roles in parasite infection, particularly irf8, which appeared UR at 1, 2, 4 and 12 hpi in turbot peritoneal cells during P. dicentrarchi infection and which regulates the production of proinflammatory cytokines during malarial infections." (PMID 33076342, 2020).
pemphigus (3 papers, 2017 to 2025). Pemphigus is a group of rare autoimmune diseases that cause blistering of the skin and mucous membranes (mouth, nose, throat, eyes, and genitals).This conditioncan occur at any age, but often strikes people in middle or older age. "By associating the co-expressed genes with GWAS results for pemphigus and SLE, IRF8 and STAT1 were characterized as the key regulatory genes." (PMID 35632621, 2022). "By associating the modular genes with genome-wide association studies (GWASs) for pemphigus and SLE, we characterized IRF8 and STAT1 as key regulatory genes." (PMID 29387060, 2017). "Differential expression analysis was conducted to investigate the expression patterns of the five genes (XBP1, FBXO45, SAT2, AIFM1, and ACSL4) and eight other DEGs associated with ferroptosis (G3BP1, WBP11, TET2, IRF8, FASN, GDPD5, H1-4, and HUWE1) in both the pemphigus and control groups." (PMID 40612574, 2025).
prostate carcinoma (3 papers, 2023 to 2025). A carcinoma that arises from epithelial cells of the prostate gland. "This includes critical roles in CRC regulation for TFs such as MYOD in rhabdomyosarcoma, AR in prostate cancer, and IRF8 in AML." (PMID 39536500, 2024). "These CRC mapping methods, along with pharmacological and genomic studies, have identified critical roles for MYOD, IRF8, FOXA1, and SOX11 TFs in rhabdomyosarcoma, acute myeloid leukaemia (AML), prostate cancer, and neuroblastoma, respectively." (PMID 39536500, 2024). "Many of the immune response related (e.g., IRF8, JAK3, PTGER4, RELB, IFITM3) and part of the lipid metabolism related genes (e.g., NR1H4, PPARGC1B, PLIN1, HSD17B14) were identified to be adaptive which addressed their significance for prostate cancer." (PMID 36809527, 2023).
retinal degeneration (3 papers, 2022 to 2025). Degeneration of the retina. "Retinal degeneration (showing increased retinal thickness) was detected to be alleviated when the expression levels of IRF8 were inhibited by immunomodulatory agents." (PMID 35565057, 2022). "In addition, in the rd1 mouse model of retinal degeneration, a lowered Irf8 expression attenuated neuroinflammation by shifting microglia polarization toward M2." (PMID 41476611, 2025). "For instance, alpha antitrypsin treatment ameliorated retinal degeneration by polarizing microglia toward the M2 phenotype, partly through the regulation of IRF4/IRF8 in rd1 mice." (PMID 36670960, 2022).
rheumatoid arthritis (3 papers, 2019 to 2025). A chronic, systemic autoimmune disorder characterized by inflammation in the synovial membranes and articular surfaces. "For example, the IRF8 + 83 kb enhancer described here contains an SNP, termed rs9927316, associated with rheumatoid arthritis." (PMID 39972074, 2025).
sarcoma (3 papers, 2022). A usually aggressive malignant neoplasm of the soft tissue or bone. "In a chemically-induced sarcoma model, an inverse relationship between IRF8 and MMP3 expression was demonstrated; in a mouse model of mammary cancer, loss of MMP3 reduced spontaneous lung metastasis." (PMID 36078039, 2022). "Mechanistically, IRF8 disruption diminishes JAK1 expression and inhibits STAT1 phosphorylation to block IFN-γ induced Fas upregulation in sarcoma cells." (PMID 36078039, 2022).
AIDS (2 papers, 2018 to 2024). A syndrome resulting from the acquired deficiency of cellular immunity caused by the human immunodeficiency virus (HIV). "Sequence variants near IRF8 have repeatedly been identified as risk factors for various AIDs including SSc12 according to the previous GWASs." (PMID 38296975, 2024).
aneurysm (2 papers, 2021 to 2025). Bulging or ballooning in an area of an artery secondary to arterial wall weakening. "In mice, DC‐specific overexpression of Irf8 exacerbates aneurysm expansion following periadventitial elastase application, while DC‐specific Irf8 deletion attenuates AAA development." (PMID 40184622, 2025). "Our findings suggest that IRF8 expression levels are upregulated in both human and murine AAA samples, potentially accelerating aneurysm development by promoting the differentiation of cDC1s and the activation of CD8+ T cells." (PMID 40184622, 2025). "Notably, IRF8 appears to have a more significant role than BATF3, as evidenced by its higher differential expression in human aneurysm tissue microarrays compared to healthy tissue." (PMID 40184622, 2025).
Arterial thrombosis (2 papers, 2023). The formation of a blood clot inside an artery. "Our laser-induced arterial thrombosis following the knockdown of irf8 showed a shortened TTO and yielded thrombotic phenotype." (PMID 37162944, 2023).
clear cell renal cell carcinoma (2 papers, 2019 to 2026). "In clear-cell renal cell carcinoma, TAMs express high levels of IRF8, contributing to CD8+ T cell exhaustion." (PMID 41596598, 2026). "Evaluation of protein expression within histologic sections of primary clear cell renal cell carcinoma patient samples showed intensity of IRF8 by CD68+ macrophages correlated inversely with stage." (PMID 31221219, 2019). "Here, we investigated whether alterations in macrophage expression of the transcriptional regulator for myeloid commitment and function, interferon regulatory factor-8 (IRF8), could predict survival of clear cell renal cell carcinoma patients." (PMID 31221219, 2019).
Cognitive impairment (2 papers, 2019 to 2022). Abnormal cognition is characterized by deficits in thinking, reasoning, or remembering. "We previously showed that a regulatory region of the interferon regulatory factor-8 (IRF8) gene is hyper-methylated in HIV-infected individuals with cognitive impairment compared to those with normal cognition." (PMID 31849969, 2019). "Higher IRF-8 levels in the myeloid cells may permit better control of HIV levels within the monocytes which may be a principle mechanism that may maintain viral quiescence and limit neuroinflammation leading to CNS injury manifesting as cognitive impairment." (PMID 31849969, 2019).
diabetic nephropathy (2 papers, 2023). "Our study explored the same platform GEO dataset for diabetic nephropathy bioinformatics analysis and identified eight potential key genes (TYROBP, ITGB2, CD53, IL10RA, LAPTM5, CD48, C1QA, and IRF8), screened eight transcription factors, and identified 93 miRNA nodes." (PMID 37113991, 2023).
diabetic retinopathy (2 papers, 2022 to 2023). "In diabetic mice, the expression of IRF8 is closely related to the activation of microglia and the regulation of the inflammatory response, thereby influencing the occurrence of diabetic retinopathy (Liu, Xu & Gao, 2021)." (PMID 37250717, 2023). "In diabetic mice, inhibited microglial activation and inflammatory response will regulate the expressions of IRF8, eventually leading to the improvement of diabetic retinopathy." (PMID 35909518, 2022).
dilated cardiomyopathy (2 papers, 2019 to 2024). Cardiomyopathy which is characterized by dilation and contractile dysfunction of the left and right ventricles. "Similarly, Qiao’s study also reported that SPI1, ZBTB7A, and IRF8 play crucial roles in the development of dilated cardiomyopathy and ischemic cardiomyopathy by regulating inflammation- and apoptosis-related genes." (PMID 31850068, 2019).
hypercholesterolaemia (2 papers, 2018). "Using dietary inducing hypercholesterolemia, mice can lead a hypomethylation state in spleen focus-forming virus proviral integration oncogene (PU.1) and interferon regulatory factor 8 (IRF8) and consequently resulted in a phenotypic alteration in monocytes and macrophages." (PMID 29410709, 2018).
influenza (2 papers, 2022 to 2025). An acute viral infection of the respiratory tract, occurring in isolated cases, in epidemics, or in pandemics; it is caused by serologically different strains of viruses (influenzaviruses) designated A, B, and C, has a 3-day incubation period, and usually lasts for 3 to 10 days. "We chose to analyze the differentiation of human B cells based on the bifurcated expression patterns of the activation-induced TFs, IRF4 and IRF8, which are observed in the murine system and also in human HA-specific B cells that emerge within one week of influenza immunization." (PMID 40667223, 2025). "Notably, a number of proteins lacking a signal peptide and not annotated as ‘secreted’ elsewhere were overrepresented in the influenza stimulated group, including the proteases cathepsin c, cathepsin z, legumain, and the transcription factor IRF8." (PMID 35401570, 2022).
ischemia (2 papers, 2016 to 2022). A hypoperfusion of the BLOOD through an organ or tissue caused by a PATHOLOGIC CONSTRICTION or obstruction of its BLOOD VESSELS, or an absence of BLOOD CIRCULATION. "Similarly, hepatic IRF-8 increase aggravates liver ischemia/reperfusion injury in mice, and the underlying mechanism is related to elevating CXCL1/9 production and neutrophil recruitment." (PMID 35637950, 2022). "This is in agreement with the expression peak of IRF-4 at day 3, a key transcription factor of M2 polarization phenotype, whereas expression of IRF-8, a transcription factor of M1 polarization phenotype, increases within 72 h after ischemia." (PMID 27539642, 2016).
lung squamous cell carcinoma (2 papers, 2016 to 2021). "In most of the cancer tissues, IRF8 get upregulated, while in some, such as in lung squamous cell carcinoma (LUSC) IRF8 is downregulated." (PMID 33673123, 2021).